SOX10 (SRY-box transcription factor 10)
Diseases named in the same sentence as SOX10 in open-access papers (continued):
Sharing a sentence is not in itself a finding about the gene and the disease.
hearing loss (13 papers, 2017 to 2025). "Both Gjb2loxP/loxP; Otog-Cre and Gjb2loxP/loxP; Sox10-Cre mice are considered models of human DFNB1 non-syndromic hearing impairment, which is frequently associated with truncating mutations that yield non-functional Cx26 proteins." (PMID 35308122, 2022). "Among the WS patients who participated in this study, all patients with SOX10 mutations have hearing loss, while some patients with PAX3 (3/7) or MITF (2/3) have." (PMID 34149797, 2021). "In this work, the inner ear morphology was investigated at different embryonic stages of the SOX10 mutation miniature porcine model with sensorineural hearing loss, and high-throughput RNA-seq and bioinformatics analyses were applied." (PMID 29922125, 2018). "Inactivating mutations in SOX10 cause Waardenburg syndrome, a rare disorder characterized by pigmentation abnormalities and hearing impairment." (PMID 29280744, 2017). "In cases of sensorineural hearing loss, various SOX10 mutations may lead to the agenesis or hypoplasia of semicircular canals and enlarged vestibules." (PMID 38132479, 2023). "Mutations in SOX10 have been associated with various forms of syndromic hearing loss." (PMID 32908489, 2020). "Our results highlight the importance of applying comprehensive diagnostic approaches such as NGS in molecular diagnosis of hearing loss and show that the p.R161C mutation in SOX10 may be associated with a wide range of variable clinical manifestations." (PMID 32908489, 2020). "Pathogenic variations in SOX10 (96.5%) and MITF (89.6%) are more frequently linked to hearing impairment than other WS associated genetic pathogenic variations." (PMID 40868272, 2025). "Hearing loss is such a penetrant phenotype in patients with SOX10 mutations that it can manifest without any other features of WS or KS, resembling isolated hearing loss." (PMID 38132479, 2023). "WS caused by SOX10 mutations can resemble nonsyndromic hearing loss in young children who do not present with pigmentary abnormality." (PMID 32908489, 2020).
malignant peripheral nerve sheath tumor (13 papers, 2018 to 2025). Malignant peripheral nerve sheath tumor (MPNST) is a rare and often aggressive soft tissue sarcoma occurring in a wide range of anatomical sites. "Malignant peripheral nerve sheath tumours are often S-100 and Sox-10 positive." (PMID 32566457, 2020). "Furthermore, data comparing genetically confirmed synovial sarcoma with malignant peripheral nerve sheath tumor with respect to SOX10 expression are limited." (PMID 33076385, 2020). "Malignant peripheral nerve sheath tumor (MPNST) is one such malignancy where the role of SOX10 has been investigated." (PMID 38132479, 2023). "SOX10 negative melanoma, clear cell sarcoma, and malignant peripheral nerve sheath tumor (MPNST) are also diagnostic possibilities." (PMID 30314519, 2018). "In our case, the absence of CD117 and DOG1 effectively ruled out GIST, while the lack of S100 and SOX10 expression argued against malignant peripheral nerve sheath tumor, and negative SMA/desmin excluded smooth muscle tumors." (PMID 41246769, 2025). "The cases of malignant peripheral nerve sheath tumour we used as controls were S-100 and Sox-10 positive, while STAT6 was negative." (PMID 32566457, 2020). "Approximately 1% of the tumor cells were S100+, CD34+, SOX10+, and MIB-1 positive, and the growth was diagnosed as a myxoid low-grade malignant peripheral nerve sheath tumor (MPNST)." (PMID 40777560, 2025). "H3K27me3 deletion, more common in malignant peripheral nerve sheath tumors (MPNST) with bone involvement, may occur in ESOS, and SOX10 expression should be checked to rule out MPNST." (PMID 40308507, 2025). "However, a malignant peripheral nerve sheath tumor (MPNST) is mostly negative for S100 protein and SOX10 and is seldom strongly and diffusely positive." (PMID 41281118, 2025).
sarcoma (13 papers, 2013 to 2025). A usually aggressive malignant neoplasm of the soft tissue or bone. "SDUS may be susceptible to EZH2 or CDK4/6 inhibition, and early evidence suggests that ERBB2/3-mutated S100/SOX10-positive sarcomas may benefit from HER2-targeted therapy." (PMID 41463261, 2025). "Collectively, we propose that Tppp3-expressing and Sox10/Krox20-negative neural crest-derived peripheral nerve cells are a cell of origin for EWS/ATF1-induced sarcomas, at least in this transgenic mouse model." (PMID 31488818, 2019). "However, in contrast to the herein presented cases, these tumors are morphologically high-grade sarcomas and are also consistently SOX10 positive." (PMID 39387892, 2024). "In addition, decisive immunohistochemistry markers for undifferentiated pleomorphic sarcoma include S100/SOX10, smooth muscle actin (SMA), and desmin." (PMID 37635229, 2023). "Taken together, we propose that Tppp3-expressing and Sox10-negative neural crest-derived peripheral nerve cells are a cell of origin for EWS/ATF1-induced sarcomas." (PMID 31488818, 2019). "None of their 5 “S100 positive sarcomas” expressed SOX10, which led the authors to conclude that in the setting of a soft tissue neoplasm SOX10 is more specific for peripheral nerve sheath tumors than S100." (PMID 24131748, 2013). "Finally, HS-PSS also showed a WT status for PRC2 genes, was assigned to the provisional and not fully characterized “MPNST-like sarcoma” methylation group, was positive for SOX10, contained an almost unaltered genome proximal to 2n but harbored a translocation generating the fusion gene EML4-ALK." (PMID 36818284, 2023). "Collectively, we concluded that Tppp3-expressing cells, but not Sox10-expressing cells, are a cell of origin for EWS/ATF1-induced sarcomas." (PMID 31488818, 2019).
triple-negative breast carcinoma (13 papers, 2018 to 2026). An invasive breast carcinoma which is negative for expression of estrogen receptor (ER), progesterone receptor (PR), and human epidermal growth factor receptor 2 (HER2). "This patient with triple negative breast cancer showed SOX-10 (+), S-100 (+), and CD117 (partially +)." (PMID 41040523, 2025). "SOX10 is a fairly sensitive marker for triple-negative breast cancer but it should always be used in conjunction with GATA3 immunohistochemical stain." (PMID 38813332, 2024). "SOX10 has been associated with CD117 and vimentin expression in triple-negative breast carcinomas, though its prognostic value remains inconclusive and is mainly considered a marker for aiding in differential diagnoses." (PMID 38132479, 2023). "Single-cell RNA sequencing revealed SOX10 as a potential driver for this plasticity, which is known among breast tumors to be almost exclusively expressed in triple-negative breast cancer (TNBC) and was also found to be highly expressed in low-ER tumors." (PMID 36859337, 2023). "Approximately 60% of triple-negative breast carcinomas have been identified using this dual-staining method, making SOX10 a useful marker in identifying epithelial neoplasms of the breast." (PMID 38132479, 2023). "We and others have recently identified Sox10 as a marker of triple-negative breast cancers (TNBC) and secretory carcinomas, often triple negative and basal-like." (PMID 33985544, 2021). "As Sox10 is a biomarker for triple-negative breast cancers (TNBC), these findings might have major implications in the targeting and treatment of those cancers." (PMID 33985544, 2021). "SOX10 positivity is usually restricted to a small subset of carcinomas (< 10%) except for triple-negative breast cancer that may more frequently express SOX10." (PMID 30205833, 2018). "Positivity is usually restricted to a small subset of carcinomas (<10%), except for triple-negative breast cancer (TNBC), which may more frequently express SOX-10." (PMID 32899175, 2020). "Therefore, the combinatorial treatment of triple-negative breast cancers with FGFR and AKT inhibitors may target two distinct signaling pathways that drive SOX10 expression by blocking both the induction and activation of Sox9." (PMID 33985544, 2021).
neuroblastoma (12 papers, 2009 to 2025). Neuroblastoma (NB) is the most common solid, extracranial childhood tumor. "A further overlapping feature with FOXR2-activated neuroblastoma is the gain of chr1q, which was found in two of our cases, and positivity for SOX10 seen in one of two cases tested." (PMID 38500181, 2024). "We transiently co-transfected mouse neuroblastoma cells (Neuro2A) with the ERBB3_MCS6 luciferase vector and with either a construct expressing wild-type Sox10 cDNA under the control of a CMV promoter (pcDNA3.1) or with an empty expression vector." (PMID 21672228, 2011). "The half-life of WT SOX10 was 8.3 hours in 501mel cells and 19.5 hours in MeWo cells, in contrast to the previously reported 6 hour half-life of SOX10 overexpressed in both HeLa cells and Neuro2A neuroblastoma cells." (PMID 29315345, 2018). "The inability to upregulate neural crest specifier genes like FoxD3, Sox10, and Snail2, essential for cell migration and differentiation, might result in the persistence of immature, proliferative cells contributing to tumorigenesis in neuroblastoma." (PMID 39404397, 2024). "Similarly, TFs linked to neural development including MYCN, PHOX2B, SOX10, and GATA3, drive high-risk neuroblastoma (NB)." (PMID 41228232, 2025). "PCPG, neuroblastoma, and NAM tissues contain Schwann-like cells called sustentacular cells detected by IHC staining for SOX10 and S10039,40." (PMID 36271074, 2022). "Since primary Schwann cells endogenously express Sox10 and are not easily transfected, the Sox10-negative but neural crest derived Neuro2a neuroblastoma cell line was used for luciferase reporter assays." (PMID 38791273, 2024). "Using CEN‐tools, we isolated such genes and revealed a subnetwork consisting of a number of transcription factors (TFs) that are known to control tissue differentiation into a specific lineage such as SOX10 in skin, PAX8 in ovary, kidney and endometrium (, and MYCN in neuroblastoma." (PMID 33073517, 2020). "Here, neuroblastoma (NB) cell line subtypes were characterized according to embryonic peripheral nervous system development markers (GAP43, Phox2b, Sox10, c-kit, GD2, NF68, vimentin, S100β, calcyclin and ABCG2), morphological features, gene expression and differentiation potential." (PMID 19216736, 2009). "SK-N-SH neuroblastoma cell was shown to express RET, NKX2-1, PHOX2B, but not SOX10, PAX3." (PMID 21677782, 2011).
vitiligo (11 papers, 2010 to 2025). Generalized well circumscribed patches of leukoderma that are generally distributed over symmetric body locations and is due to autoimmune destruction of melanocytes. "Among these were the associations of KHDC3L with ovarian insufficiency, RFX6 with diarrheal-type intestinal dysfunction, CYP11A1 (also known as cholesterol side chain cleavage enzyme) with adrenal insufficiency (AI), and SOX10 with vitiligo." (PMID 32410729, 2020). "The transcription factors SRY-box 9 (SOX9) and SRY-Box 10 (SOX10) were reported to be vitiligo autoantigens in APS-1 patients with autoantibodies detected in 15 and 22% of sera, respectively." (PMID 30002654, 2018). "Autoantibodies against TPH have been associated with alopecia, vitiligo, and enamel dysplasia and anti-SOX9/SOX10 antibodies with vitiligo." (PMID 27597936, 2016). "In total, we investigated the levels of SOX10 in 195 patients, 85 with vitiligo and 110 with MM, and compared the levels to those of 85 healthy controls, demonstrating the added value of SOX10 measurement in MM." (PMID 27110718, 2016). "For the vitiligo cohort we observed increased levels of SOX10 in 51 (60%) out of the 85 analyzed sera." (PMID 27110718, 2016). "Furthermore, we detected elevated SOX10 levels in vitiligo patients, suggesting that SOX10 is released from melanocytes by similar mechanisms in vitiligo and MM." (PMID 27110718, 2016). "We detected markedly elevated levels of SOX10 in the circulation of vitiligo patients." (PMID 27110718, 2016). "Notably, auto-antibodies against the transcription factors SOX9 and SOX10, important in the development of melanocytes, have been detected in APECED patients and are highly associated with skin symptoms such as vitiligo." (PMID 22506061, 2012). "Several melanocyte autoantigens have been detected in vitiligo patients including tyrosinase, tyrosinase-related protein 1, tyrosinase-related protein 2, melanosomal matrix protein gp 100 (Pmel17), melanocyte transcription factor (SOX10), and melanin concentrating hormone receptor 1 (MCHR1)." (PMID 29362715, 2017). "However, in vitiligo and MM sera, SOX10 was found in much higher frequencies." (PMID 27110718, 2016). "Furthermore, SOX9 and SOX10 transcription factors are vitiligo autoantigens in APECED." (PMID 21197407, 2010). "The down regulation of SOX10 and PLP1 in vitiligo lesional skin may also be partially explained by the fact that they can be found in melanocytes." (PMID 23251420, 2012).
uveal melanoma (10 papers, 2012 to 2026). A melanoma derived from melanocytes of the uveal tract. "Mutations in the SOX-10 gene have been associated with uveal melanoma." (PMID 34355005, 2021). "SOX10 is essential for melanocyte development and maintenance and plays a critical role in uveal melanoma (UM) initiation and progression." (PMID 42120529, 2026). "We used Melan A and SOX10 immunohistochemistry tests to identify uveal melanoma cells in the nodules." (PMID 35056909, 2021). "SOX-10 expression proves to be the most sensitive marker for uveal melanoma; however, its specificity is less than optimal due to positivity in normal ocular structures." (PMID 26316887, 2015). "SOX-10 showed exclusive nuclear positivity, as previously reported, in 100% of the uveal melanoma cases (38/38)." (PMID 26316887, 2015). "In this study, we sought to compare the utility of the most commonly used uveal melanoma marker HMB-45 to the recently described SOX-10." (PMID 26316887, 2015). "A total of 40 tissue blocks of enucleated eyes with uveal melanoma were cut and stained using an anti-SOX-10 mouse monoclonal antibody and HMB-45 antibody." (PMID 26316887, 2015). "Our results from 38 tumours indicate that SOX-10 provides a highly sensitive marker for uveal melanoma (38/38)." (PMID 26316887, 2015). "SOX-10 expression proved to be the most sensitive marker for uveal melanoma, and therefore, we propose a modified panel for the diagnosis of uveal melanoma that includes both SOX-10 and HMB-45." (PMID 26316887, 2015). "SOX-10 can be useful when analysing heavily pigmented uveal melanoma." (PMID 26316887, 2015). "Therefore, we propose a modified panel for the diagnosis of uveal melanoma that includes both SOX-10 and HMB-45." (PMID 26316887, 2015). "This study aimed to evaluate Sox-10 expression in uveal melanoma." (PMID 26316887, 2015). "These FNA specimens may have retinal pigmented epithelial cells, which can be positive for SOX-10, mimicking uveal melanoma cells." (PMID 26316887, 2015). "SOX-10 showed exclusive nuclear positivity in 100% of the uveal melanoma cases (38/38)." (PMID 26316887, 2015). "Studying eyes from the autopsies of patients with uveal melanoma, along with other patients known to have carcinomas such as breast, colon, and lung, can provide a great objective method to demonstrate the utility of SOX-10 in these clinical scenarios." (PMID 26316887, 2015). "Their results serve as an independent validation for the expression of SOX-10, along with HMB-45 in uveal melanoma." (PMID 26316887, 2015). "This concise panel replaces less sensitive markers, such as S-100 with SOX-10, and eliminates the redundant use of Melan-A, which has the same sensitivity as HMB-45 for uveal melanoma." (PMID 26316887, 2015). "Because immunohistochemical staining against LCA, PAX-5, and SOX-10 was negative, we excluded the possibility of B-cell lymphoma and uveal melanoma." (PMID 34355005, 2021). "To date, no published study has compared the SOX-10 staining pattern to the current, most reliable marker for uveal melanoma, HMB-45 in human enucleated eye samples." (PMID 26316887, 2015). "Importantly, analyses of TCGA data confirmed that high expression of PAX3, SOX10, MITF and TFAP2A are defining features of uveal melanoma patient samples and such TFs have been validated as selective cancer dependencies in UM cell lines by large-scale functional genomics screens." (PMID 37400441, 2023). "Therefore, we suggest using a panel of SOX-10 and HMB-45 for diagnosing primary uveal melanoma." (PMID 26316887, 2015). "To date, we are not aware of any study comparing the staining pattern of SOX-10 in uveal melanoma to the staining pattern of HMB45, which is considered to be the most sensitive marker for uveal melanoma in clinical practice." (PMID 26316887, 2015).
hepatocellular carcinoma (9 papers, 2014 to 2025). A malignant tumor that arises from hepatocytes. "SOX10 contributes to tumorigenesis in hepatocellular carcinoma (HCC)." (PMID 32675943, 2020). "Further, epigenetic alterations of the EDNRB gene, a target of SOX10, might play an important role in the pathogenesis of hepatocellular carcinoma." (PMID 28347313, 2017). "For example, SOX10 facilitates the formation of a stable SOX10/T-cell factor (TCF)-4/β-catenin complex, subsequently contributing to tumorigenesis in hepatocellular carcinoma (HCC)." (PMID 25427424, 2014).
megacolon (9 papers, 2008 to 2024). "A genome-wide scan in mice suggested that multiple modifier intervals are correlated with the severity of aganglionosis in Sox10 (Dom) mice and provided additional evidence of the multi-genic effects that contribute to aganglionic megacolon." (PMID 25790447, 2015). "It was shown previously that the Sox10-rtTA heterozygous mice also display pigmentation abnormalities and megacolon although at much lower frequency and of less severity." (PMID 20187849, 2010). "In a similar fashion, mutations in the mouse Sox10 gene yield mice with impaired pigmentation and megacolon, and such models have been critical for understanding the expression and function of Sox10." (PMID 18773071, 2008). "DOX-induced activation of Runx1a in Sox10-rtTA/TRE-Runx1a embryos resulted in offspring of smaller size than normal litter-mates, and with early postnatal lethality, cutaneous pigmentation defects, megacolon, and reduced DRG size." (PMID 20187849, 2010).
salivary gland tumors (9 papers, 2015 to 2024). "Despite this, SOX10 is considered a valuable protein expression marker for the diagnostic identification of salivary gland neoplasms, contributing to increased diagnostic accuracy." (PMID 38132479, 2023). "In the context of salivary gland neoplasms, SOX10 expression has been identified in tumors arising from acinar and intercalated ductal cells." (PMID 38132479, 2023). "At the best of our knowledge, only rare cases of salivary glands tumors with abundant melanin pigment and/or expression of multiple melanocytic markers (S-100, SOX10, HMB45, MART-1 and MITF) have been reported in the literature." (PMID 33591488, 2021). "Keeping in view the expression of SOX10 in normal myoepithelial cells of breast and salivary gland tumors with myoepithelial differentiation, the higher expression of SOX10 in TNBC and ER- tumors can be explained by their basal-like or myoepithelial differentiation." (PMID 38813332, 2024). "Interestingly, a recent study of basaloid SCC showed that a majority of tumors were positive for SOX10, a feature shared with most cylindromas, as well as some many other cutaneous adnexal tumors and salivary gland tumors." (PMID 32892208, 2021). "However, certain salivary gland neoplasms either show no SOX10 representation or exhibit focal expression in staining." (PMID 38132479, 2023).